CYP3A4 (cytochrome P450 family 3 subfamily A member 4)
Diseases named in the same sentence as CYP3A4 in open-access papers (continued):
Sharing a sentence is not in itself a finding about the gene and the disease.
leukemia (8 papers, 2009 to 2024). A malignant (clonal) hematologic disorder, involving hematopoietic stem cells and characterized by the presence of primitive or atypical myeloid or lymphoid cells in the bone marrow and the blood. "Similarly, polymorphisms in CYP3A4 (which converts epipodophylotoxins into catechol metabolites) have been associated with an increased risk of leukemia." (PMID 21637673, 2009). "CYP3A4, the liver's major drug-metabolizing enzyme, was at least partially responsible for BM stroma's ability to protect multiple myeloma (MM) and leukemia cells from bortezomib and etoposide, respectively, both in vitro and in vivo." (PMID 25915157, 2015). "Not only did CYP3A4 knockdown reverse the augmentation of BMSC‐mediated chemoprotection that is associated with MRD biology (ie chemotherapy effect including low leukaemia burdens and diminished inflammation), but the CYP3A4 inhibitor clarithromycin had similar activity." (PMID 30920135, 2019). "Furthermore, ISA is a mild/moderate CYP3A4 inhibitor with fewer drug interactions compared with posaconazole and voriconazole, which is safer for leukemia patients who may require targeted drugs such as venetoclax." (PMID 38978781, 2024).
melanoma (8 papers, 2016 to 2025). A malignant, usually aggressive tumor composed of atypical, neoplastic melanocytes. "However, melanomas showed greater loss of drug metabolizing capacity due to downregulation of the CYP3A4 gene." (PMID 26901218, 2016). "The anti-melanoma effect of S. nigrum is likely through the modulation of three unique melanoma-related gene targets(CYP3A4, GBA2 and PTK6) by its two unique active ingredients (diosgenin and solanocapsine)." (PMID 40636215, 2025). "Our data show that three unique melanoma-related gene targets (CYP3A4, GBA2and PTK6) for two unique active ingredients (diosgenin and solanocapsine) present in S. nigrum have potential role." (PMID 40636215, 2025). "Nevertheless, suppression of CYP3A4 levels in inflammatory diseases, can improve drug metabolism and value of therapeutic drugs for melanoma and psoriasis." (PMID 30999678, 2019). "On the other hand, the expression of VDR and its splicing variants and other vitamin D related genes (RXR, PDIA3, CYP3A4, CYP2R1, CYP27B1, CYP24A1 and CYP11A1) was detected in WM98 and A375 melanomas with the transcript levels being modulated by vitamin D analogs." (PMID 30200275, 2018). "Three genes (CYP3A4, GBA2 and PTK6) were identified to besignificantly downregulated in melanoma patients." (PMID 40636215, 2025). "CYP11A1, CYP24A1, CYP27B1, CYP2R1, and CYP3A4 are expressed in WM98 and A375 human melanoma cell lines." (PMID 38672780, 2024). "Cediranib treatment resulted, however, in an increase in mRNA level for CYP3A4 and CYP2R1 in melanoma cells pretreated with 1,25(OH)2D3 (p < 0.05 vs. control and vs. monotreatment, respectively)." (PMID 35004285, 2021). "Therefore, we conclude thatgenes CYP3A4 and PTK6, which are modulated by diosgenin, are likely to be the major targets conferring S. nigrum theanti-melanoma effect." (PMID 40636215, 2025). "CYP27A1, CYP27B1, and CYP2R1 are involved in the activation of vitamin D, whereas CYP24A1 and CYP3A4 are responsible for the degradation of the active vitamin D. CYP24A1, the primary catabolic enzyme of calcitriol, is overexpressed in melanoma tissues and cells." (PMID 38672780, 2024). "Interestingly, the strongest decrease in the mRNA levels of CYP3A4 and CYP2R1 was observed in A375 melanoma cells treated with 21(OH)pD." (PMID 30200275, 2018).
torsades de pointes (8 papers, 2006 to 2025). A malignant form of polymorphic ventricular tachycardia that is characterized by heart rate between 200 and 250 beats per minute, and qrs complexes with changing amplitude and twisting of the points. "These include documented instances of torsades de pointes or cardiac arrest when amiodarone was used in combination with agents such as fluoxetine, metronidazole, ciprofloxacin, sotalol, clarithromycin, and fluconazole, often involving CYP3A4-related interactions and additive QTc effects." (PMID 41024894, 2025).
Adrenal insufficiency (7 papers, 2012 to 2025). Insufficient production of steroid hormones (primarily cortisol) by the adrenal glands. "For nearly a decade, this medication was the only orally available antifungal agent, but it has been conclusively linked to potentially severe safety issues (hepatoxicity, adrenal insufficiency, and Cytochrome P450 3A4 (Cyp3A4) mediated drug/drug interaction)." (PMID 37214226, 2022). "Itraconazole is an even more potent inhibitor of CYP3A4, and secondary adrenal insufficiency was reported to occur in a patient on inhaled fluticasone and itraconazole." (PMID 37274338, 2023). "This is different for the potent CYP11B1 inhibitors posaconazole and itraconazole where cases with adrenal insufficiency and hyperplasia have been described, mainly due to cross-reactions with other drugs depending on functional CYP3A4 or in combination with unrelated diseases." (PMID 39175536, 2024). "It was demonstrated in a young CF patient that adrenal insufficiency may develop rapidly and at comparatively low ICS doses if the activity of CYP3A4, the major glucocorticoid metabolizing enzyme, is reduced by other drugs such as the antifungal Fluconazole." (PMID 23056987, 2012).
Arrhythmia (7 papers, 2010 to 2024). Any cardiac rhythm other than the normal sinus rhythm. "For example, ketoconazole and quinidine are well-known CYP3A4 inhibitors that can induce life-threatening heart rhythm disorders when co-administered with other substrates of CYP3A4, such as erythromycin." (PMID 21876481, 2011).
benign prostatic hyperplasia (7 papers, 2003 to 2025). A non-cancerous nodular enlargement of the prostate gland. "On the other hand, it has been reported that the incidence rate of PCa is higher in patients with benign prostatic hyperplasia having the CYP3A4*1B allele compared to those having the CYP3A4*1A allele." (PMID 24924803, 2014).
Hypercholesterolemia (7 papers, 2012 to 2025). An increased concentration of cholesterol in the blood. "CYP3A4 activity was further monitored with the clinically-relevant substrate LVS, an anti-hypercholesterolemia drug." (PMID 23667566, 2013).
liver cirrhosis (7 papers, 2007 to 2026). "We report a patient with cystic fibrosis, liver cirrhosis and preexisting pancytopenia grade 1, requiring multiple concomitant medications inhibiting CYP3A4 and P-gp, who presented with metastatic seminoma." (PMID 41632323, 2026). "No data on the in vivo clearance for CYPs in HCC patients was identified in a literature search, and only data regarding the clearance for CYP2C19 (67±40 ml/min) and CYP3A4/5 (319.49±154.42 ml/min) in liver cirrhosis were queried." (PMID 27086920, 2016). "The observed negative correlation (but not significant) between the urinary values of 6 β-OHC/C and both ALT and prothrombin time in our results reflected a trend of CYP3A4 activity to reduce in liver cirrhosis." (PMID 19690646, 2007). "Therefore, hypoalbuminemia in patients with liver cirrhosis may result in alteration in the proposed protein-facilitated metabolism of drugs and endogenous substances (e.g. cholesterol & sex steroids) which are metabolized by CYP3A4." (PMID 19690646, 2007). "Moreover, previously published pharmacokinetic studies have demonstrated that clearance for CYP3A4/5 was markedly decreased in patients with either cirrhosis or severe alcoholic cirrhosis, while the clearance for CYP2C19 was also significantly reduced in patients with liver cirrhosis." (PMID 27086920, 2016).
non-alcoholic fatty liver disease (7 papers, 2017 to 2024). "Both non-alcoholic fatty liver disease (NAFLD) and DM have been associated with decreased expression and activity of hepatic CYP3A4." (PMID 38347465, 2024). "For example, it has been shown that in non-alcoholic fatty liver disease, changes in the levels of miR-150-5p and miR-200a-3p can post-transcriptionally suppress CYP3A4, whereas miR-34a, miR-30c-1-3p and miR-27b suppress CYP3A4, affecting RXRa, PXR and VDR." (PMID 36359206, 2022). "There is evidence that changes in hepatic levels of some miRNAs, in particular miR-150-5p and miR-200a-3p in nonalcoholic fatty liver disease can post-transcriptionally modulate the expression of CYP3A4." (PMID 36359206, 2022). "Enzymatic activity and mRNA expression of CYP3A4 are low in patients with nonalcoholic fatty liver disease, and this observation is confirmed by experiments on mice in vivo and on cultured cells in vitro." (PMID 36359206, 2022). "Nonalcoholic fatty liver disease is reported to correlate with reduced expression and function of CYP3A4." (PMID 36359206, 2022). "In obese patients suffering from non-alcoholic fatty liver disease (NAFLD), CYP3A4 activity did not change following bariatric surgery." (PMID 38590638, 2024).
non-small cell lung carcinoma (7 papers, 2022 to 2026). A group of at least three distinct histological types of lung cancer, including non-small cell squamous cell carcinoma, adenocarcinoma, and large cell carcinoma. "Paclitaxel (PTX), which is utilized in the treatment of non-small cell lung cancer, undergoes metabolism via CYP3A4." (PMID 42199866, 2026). "Our case provides evidence that osimertinib 160 mg can be safely administered concurrently with a known CYP3A4 inducer while preserving efficacy in CNS metastatic EGFR positive non-small cell lung cancer." (PMID 40256355, 2025). "Vinorelbine is one of the alkaloid chemotherapeutic drugs with curative effects for non-small cell lung cancer patients, which promotes cell death mainly by disturbing the microtubule dynamics, and whose metabolism is mainly conducted in the liver, and mainly catalyzed by CYP3A4." (PMID 35887201, 2022). "Our case illustrates that 160 mg of osimertinib administered concurrently with a strong CYP3A4 inducer can be given safely and with retained efficacy in treating CNS metastatic EGFR-positive non-small cell lung cancer." (PMID 40256355, 2025). "On the contrary, poziotinib (a tyrosine kinase inhibitor employed in HER2 exon 20 mutant Non-Small Cell Lung Cancer, NSCLC), mainly metabolized by CYP3A4, was found to significantly inhibit the metabolism of vonoprazan." (PMID 39145848, 2024). "CYP3A4 is a critical enzyme in the cytochrome P450 family, responsible for metabolizing about 50% of all clinically used drugs, including several TKIs such as imatinib, erlotinib, and gefitinib, used to treat chronic myeloid leukemia (CML) and non-small cell lung cancer (NSCLC)." (PMID 40149251, 2025).
acute myeloid leukemia (6 papers, 2015 to 2022). Acute myeloid leukemia (AML) is a group of neoplasms arising from precursor cells committed to the myeloid cell-line differentiation. "CYP3A4 levels in BM stroma were about 30–50% of the levels in HepG2 cells, whereas its expression was barely detectable in acute myeloid leukemia (AML) (Kasumi 1, OCI-AML3 and KG1) and multiple myeloma (MM) (H929 and RPMI 8226) cells." (PMID 25915157, 2015). "Midostaurin is a novel agent for FLT3-TKD/-ITDmut-acute myeloid leukemia (AML) and metabolized via cytochrome P450 3A4 (CYP3A4)." (PMID 32514626, 2020).
atrial fibrillation (6 papers, 2016 to 2024). A disorder characterized by an electrocardiographic finding of a supraventricular arrhythmia characterized by the replacement of consistent P waves by rapid oscillations or fibrillatory waves that vary in size, shape and timing and are accompanied by an irregular ventricular response. "Digoxin, an anti-arrhythmic and heart failure medication commonly used in atrial fibrillation patients, is partially metabolized by CYP3A4." (PMID 38590638, 2024). "We speculate a significant interference on adverse events (mainly atrial fibrillation and consequently acute coronary syndromes) and on the outcome of unfavorable interactions between ivabradine and diltiazem, verapamil and strong inhibitors of CYP3A4 (4.6% of the total population)." (PMID 29736470, 2016).
Hypokalemia (6 papers, 2010 to 2025). An abnormally decreased potassium concentration in the blood. "Other notable side effects include hypokalemia, headaches, thirst and drug interactions due to competition between vaptans and other CYP3A4 substrates." (PMID 26553121, 2015). "QTc prolongation in COVID‐19 may be medication induced or due to increased cytokine which can lead to stimulation of myocyte ion channels and inhabitation of enzyme CYP3A4 or due to abnormal electrolytes including hypokalemia or hypomagnesemia (Pornwattanakavee, Priksri, and Leelakanok 2021)." (PMID 39394768, 2024).
neuropathy (6 papers, 2017 to 2025). A disorder affecting the nervous system that manifests with pain, tingling, numbness, and/or muscle weakness. "The same study showed that the CYP3A4*1B 392AA and AG alleles are predictive of only grade >1 neuropathy, (OR 2.26, 95% CI: 1.03–4.94, P = 0.038)." (PMID 29163177, 2017). "CYP3A4*22 carriers were correlated with an increased risk of severe neuropathy (P = 0.043)." (PMID 29163177, 2017).
rheumatoid arthritis (6 papers, 2021 to 2023). A chronic, systemic autoimmune disorder characterized by inflammation in the synovial membranes and articular surfaces. "Based on sparse data from three patients, continuous anti-IL-6R therapy seems to cause an acute but transient increase in CYP3A4 activity in rheumatoid arthritis patients, which may be due to a normalization of the inflammation-suppressed CYP activity." (PMID 37831074, 2023). "Based on the primary endpoint midazolam metabolic ratio, we observe a slight trend towards a weak increase in CYP3A4 activity in patients with rheumatoid arthritis after 3 weeks of anti-IL-6R therapy." (PMID 37831074, 2023). "Clinical studies have shown a > 50% lower simvastatin (CYP3A4 substrate) exposure 1 week after a single anti-IL-6R dose in patients with rheumatoid arthritis, indicating a normalization (increase) in CYP3A4 activity." (PMID 37831074, 2023). "Among three patients with rheumatoid arthritis, we demonstrated a trend towards increased CYP3A4 activity after 3 weeks of anti-IL-6R therapy, which normalized to baseline after 12 weeks of treatment." (PMID 37831074, 2023). "In another work, patients with rheumatoid arthritis also manifested lower plasma concentrations of 4-β-hydroxycholesterol (an endogenous metabolite of CYP3A4) than did healthy controls." (PMID 36359206, 2022). "Blocking IL-6 receptors, via the monoclonal antibodies tocilizumab and sarilumab has reversed CYP3A4 activity suppression in rheumatoid arthritis patients." (PMID 35185562, 2022). "This work aimed to find new inhibitors of the CYP3A4 and JAK3 enzymes, which are significant players in autoimmune diseases such as rheumatoid arthritis." (PMID 38202604, 2023). "Voriconazole, a triazole antifungal drug, inhibits the cytochromes CYP3A4 and CYP2C, and tofacitinib, a Janus kinase inhibitor for the treatment of rheumatoid arthritis, is metabolized by CYP3A4 and CYP2C19 in humans." (PMID 34069798, 2021). "In patients with rheumatoid arthritis, a negative correlation of the levels of IL-1RA, IL-6, and CXCL8 with the expression of the CYP3A4 phenotype of the CYP family was detected." (PMID 35408801, 2022).
rickets (6 papers, 2020 to 2025). Bone softening and weakening usually caused by deficiency or impaired metabolism of vitamin D. Deficiency of calcium, magnesium, or phosphorus may also cause rickets. "In support of this, a de novo cyp3a4 missense mutation (c.902T>C) that resulted in a 10-fold increase in CYP3A4 activity was revealed in two patients with rickets that had low concentrations of calcidiol and calcitriol in their serum." (PMID 40871701, 2025). "Further, cytochrome P450 (CYP) enzyme 3A4 (CYP3A4) can also oxidize 25(OH)D and 1,25(OH)D2 into 4β-hydroxylated, inactivated substrates, as shown in patients with rickets due to CYP3A4-activating mutations." (PMID 39125269, 2024). "VDDR3 is a rare autosomal dominant form of rickets due to gain-of-function missense mutation in the CYP3A4 gene that leads to an increased and rapid inactivation of vitamin D metabolites." (PMID 34199067, 2021). "Pathologies such as vitamin D–dependent rickets and osteoporosis can progress because of the inactivating effect of CYP3A4 on the active form of vitamin D." (PMID 36359206, 2022).
thyroid cancer (6 papers, 2019 to 2025). "Similarly, the CYP3A4*1G variant has been associated with reduced systemic exposure to lenvatinib in Japanese thyroid cancer patients." (PMID 40872584, 2025). "The effect of CYP3A4/5 and ABC transporter genetic polymorphism on lenvatinib was studied in an Asian population, both on healthy and thyroid-cancer patients." (PMID 40732249, 2025). "A Japanese study evaluated the effect of CYP3A4-5 and ATP-binding cassette transporter (ABCC2) polymorphisms on lenvatinib pharmacokinetics in patients with thyroid cancer." (PMID 36982571, 2023). "In this study, we aimed to evaluate how CYP3A4/5 and ABC transporter polymorphisms affected the mean steady-state dose-adjusted plasma trough concentrations (C0) of lenvatinib in a cohort of 40 Japanese patients with thyroid cancer." (PMID 30931962, 2019).
co-infection (5 papers, 2016 to 2024). "In conclusion, this study highlights the significant increase in CYP2B6 gene expression associated with co-infection, a significant association of the presence of HIV infection with the increase in CYP3A4 mRNA levels, and a trend observed for the downregulation of ABCB1 in patients using lamivudine." (PMID 37512019, 2023).
Cushing syndrome (5 papers, 2012 to 2025). Cushing's syndrome (CS) encompasses a group of hormonal disorders caused by prolonged and high exposure levels to glucocorticoids that can be of either endogenous (adrenal cortex production) or exogenous (iatrogenic) origin. "Combination of darunavir with corticosteroids should be avoided because either the inhibition of CYP3A4 increase the risk for Cushing’s syndrome or the induction of CYP3A4 from corticosteroids may reduce the concentration of darunavir." (PMID 34770225, 2021). "Carbamazepine, through its enzyme-inducing effect on CYP3A4, likely interfered with the dexamethasone suppression test, leading to false-positive results for Cushing syndrome." (PMID 40443919, 2025). "Iatrogenic Cushing syndrome was shown in this patient with inhaled FP and a CYP3A4 inhibitor, fluconazole." (PMID 22958272, 2012). "Rapid improvement in patients with Cushing's syndrome and increased hydrocortisone dose requirement during mitotane therapy may thus be explained by decreased bioavailability of oral cortisol due to rapid conversion by CYP3A4 in the liver, perhaps during a first pass after adsorption from the gut." (PMID 23781302, 2012).
heart failure (5 papers, 2017 to 2024). Inability of the heart to pump blood at an adequate rate to meet tissue metabolic requirements. "In the stepwise multiple linear regression model, eGFR, female sex, history of heart failure, body weight, age, and use of moderate or strong inhibitors of CYP3A4 or Pgp remained independent significant determinants of anti-Xa activity (p < 0.05)." (PMID 31249919, 2017).
Hyperglycemia (5 papers, 2016 to 2025). An increased concentration of glucose in the blood. "In conclusion, we show for the first time that PHHs exposed to hypo- and hyperglycemia can remain highly functional, but display increased CYP3A4 activity and selective insulin resistance, respectively." (PMID 27312339, 2016). "Taken together, the evidence implied that hyperglycemia may downregulate the enzyme activity of CYP3A4/5 responsible for the metabolism of KM." (PMID 34054521, 2021). "The TKI undergoes CYP3A4-dependent oxidative transformation, which may be influenced by hyperglycaemia." (PMID 32016844, 2020). "Increased CYP3A4 and CYP2E1 activities have also been reported by us, as well as other researchers in hyperglycemia under diabetic conditions, as well as under in vitro conditions of nutrient overload." (PMID 31443411, 2019).